GAS1 (growth arrest specific 1)
Description:
Coreceptor required for sonic hedgehog (SHH) handoff to its receptor: binds to the dually lipid-modified Sonic hedgehog protein N-product (ShhN) downstream of the CDON-BOC heterodimer and directly transfers ShhN to its patched receptor (PTCH1 or PTCH2), followed by activation of the smoothened signaling pathway. Specifically recognizes and binds palmitate and cholesterol moieties in dually lipid-modified ShhN. Binds 20(S)- hydroxycholesterol (20(S)-OHC) (By similarity). Acts as a growth arrest protein involved in growth suppression by blocking entry to S phase.
Tractability: Small molecule: a structure with a bound ligand is known. Antibody: its Gene Ontology location is reachable by antibodies, with high confidence; UniProt places it where antibodies can reach, with medium confidence; UniProt predicts a signal peptide or a membrane-spanning region. PROTAC: ubiquitination databases record sites on it.
Gene: Protein-coding gene on chromosome 9 (86,944,362 to 86,947,506, reverse strand). Ensembl gene ENSG00000180447.
Subcellular location: Cell membrane
Subcellular location (Human Protein Atlas): Nuclear speckles
Pathways (Reactome):
Signal Transduction: Activation of SMO; Ligand-receptor interactions
Gene Ontology:
Molecular function: protein binding; protein carrier chaperone; oxysterol binding
Biological process: cellular response to vascular endothelial growth factor stimulus; negative regulation of mitotic cell cycle; negative regulation of protein processing; positive regulation of smoothened signaling pathway; regulation of ER to Golgi vesicle-mediated transport; cell fate commitment; developmental growth; regulation of apoptotic process; regulation of smoothened signaling pathway; negative regulation of apoptotic process; negative regulation of cell growth; odontogenesis; regulation of cell cycle
Cellular component: plasma membrane; membrane
Genetic constraint (gnomAD): Loss-of-function variants: 8 observed, 7.34 expected, observed/expected ratio (o/e) 1.09, 90% interval 0.63 to 1.79. That is too few expected variants to judge how well the gene tolerates losing a copy. Missense variants: 518 observed, 355.94 expected, observed/expected ratio (o/e) 1.46, 90% interval 1.35 to 1.57. Synonymous variants: 293 observed, 175.03 expected, observed/expected ratio (o/e) 1.67, 90% interval 1.52 to 1.84.
Gene-disease validity (ClinGen):
ClinGen rates the evidence that GAS1 causes each of these diseases.
holoprosencephaly (autosomal dominant): Limited. Holoprosencephaly (HPE) is a complex brain malformation resulting from incomplete cleavage of the prosencephalon, occurring between the 18th and 28th day of gestation, and affecting both the forebrain and face, which results in neurological manifestations and facial anomalies of variable severity.
Homologues: Orthologues: chimpanzee GAS1 (98% identical), macaque GAS1 (97% identical), pig GAS1 (94% identical), mouse Gas1 (84% identical), rat Gas1 (83% identical), dog GAS1 (73% identical), tropical clawed frog gas1 (48% identical), zebrafish gas1b (36% identical), zebrafish gas1a (33% identical).
Diseases named in the same sentence as GAS1 in open-access papers:
GAS1 is named in the same sentence as 67 diseases in open-access papers, as found by Europe PMC text mining. Sharing a sentence is not in itself a finding about the gene and the disease. The quoted sentences say what the papers report.
breast carcinoma (10 papers, 2016 to 2024). "Notably, however, we did not observe any associations with other traits for SFTPB, EGFR, and GAS1, which were associated with a lower risk of lung adenocarcinoma and a higher risk of breast cancer overall and triple-negative breast cancer, respectively." (PMID 38684708, 2024). "In triple-negative breast cancer, NOTCH4 transcriptionally upregulated SLUG and GAS1 to maintain mesenchymal-like characteristics of breast cancer stem cells." (PMID 37386521, 2023). "Survival analysis was used to study the relation of NOTCH4, SLUG and GAS1 with prognosis of breast cancer." (PMID 32104513, 2020). "Gas1 activity detains tumour growth by inhibiting the proliferation of breast cancer cells and has been reported to play the same mechanistic role in a variety of other cancers; such as colorectal carcinoma, papillary thyroid carcinoma and glioma." (PMID 27811357, 2016). "GAS1 appeared to have a relatively specific association with risk of triple negative breast cancer [OR: 1.88, 95% CI: 1.42 to 2.47; PP4: 0.86] but was also associated with a lower risk of HER2 enriched breast cancer [OR: 0.46, 95% CI: 0.27 to 0.78; PP4: 0.78]." (PMID 38684708, 2024). "Gas1 is a well-known growth arrest protein that has been proven to block the transition of the G0 to the S phase in fibroblasts, glioblastomas, and breast cancer cells." (PMID 27391369, 2016). "Thus far, Twist-induced lncRNA-Hh has been characterized only in breast cancer where it directly targets growth arrest-specific 1 (GAS1) to initiate Hh signaling in breast cancer, promoting SOX2 and OCT4 expression, EMT, tumorigenesis, and cells with CSC properties." (PMID 32244924, 2020). "Notably, we did not observe evidence that GAS1 had a similar effect on the risk of other molecular subtypes of breast cancer or on non-cancer phenotypes, which may imply GAS1 has a specific effect to increase TNBC risk." (PMID 38684708, 2024). "We also confirmed the expression of NOTCH4, SLUG, GAS1 and CCND1 in different subtypes of breast cancer cell lines and observed expected expression patterns." (PMID 32104513, 2020). "In case of glioma or breast cancers, the GDNF-Ret signaling pathway can be blocked by GAS1 (growth arrest-specific 1) or by some Ret kinase inhibitors leading to the impairment of tumor growth." (PMID 32252363, 2020). "Indeed, GAS1 has been reported to induce apoptosis in cancer, such as glioma 47 and breast 48, and SLUG has been demonstrated to inhibit apoptosis in breast cancer and is essential for the survival of cancer cells during metastasis." (PMID 32104513, 2020). "Overexpression of lncRNA-Hh in breast cancer cells increases Hh signaling accompanied by elevated levels of SOX2 and OCT4 via targeting to GAS1 (growth arrest specific 1), and consequently contributes to activation of EMT, CSC maintenance and tumorigenesis of breast cancer cells." (PMID 28872613, 2017).
holoprosencephaly (9 papers, 2013 to 2023). "The deletion of Gas1 in mice causes microform holoprosencephaly with partial loss of SHH signalling in target cells, but the additional loss of a single Shh allele in Gas1−/− mice caused a more severe phenotype, showing that GAS1 also interacts with SHH." (PMID 34576017, 2021). "Multiple mutations in HH co-receptors have been identified in human patients with holoprosencephaly, including in GAS1 in combination with SHH mutation and CDON which usually results in the microform type of holoprosencephaly." (PMID 34576017, 2021). "Impaired function of BOC, CDON, and GAS1 appears to underlie holoprosencephaly, both in humans and in mice." (PMID 29492654, 2018). "Humans with mutations in GAS1 also present with minor forms of holoprosencephaly, including maxillary hypoplasia, hypoplastic nasal septum and cleft lip or palate." (PMID 23537390, 2013). "Triple mutants deficient in the three receptors Gas1, Cdo, and Boc display severe forebrain and cardiovascular defects at e8.5, and later holoprosencephaly, cyclopia, and neural tube pattern defects, which resemble the Shh/Ihh compound or Smo knockout phenotypes." (PMID 31781166, 2019). "However, Gas1−/−; Boc−/− mutants have lobar holoprosencephaly associated with clefting of the lip, palate and tongue, secondary to reduced sonic hedgehog transduction in the central nervous system and face." (PMID 25063195, 2014). "The deletion of Gas1 or Cdon results in holoprosencephaly phenotypes but Boc deletion in a Gas1 null background partially rescues the holoprosencephaly and facial defects." (PMID 34576017, 2021). "Gas1-/- mice display microform holoprosencephaly, including mid face hypoplasia, cleft palate and maxillary incisor fusion." (PMID 23537390, 2013). "Boc-null embryos display normal neural patterning, and Gas1-null mice show mild holoprosencephaly." (PMID 38201225, 2023). "However, Cdon/Boc and Cdon/Gas1 double mutants exhibit more severe forms of holoprosencephaly than any single mutant." (PMID 38201225, 2023). "Collectively, this phenotype demonstrates both redundancy and individual requirements for Gas1 and Boc during sonic hedgehog transduction in the craniofacial midline and suggests BOC as a potential digenic locus for lobar holoprosencephaly in human populations." (PMID 25063195, 2014).
pancreatic cancer (9 papers, 2013 to 2022). "Combined treatment of pancreatic cancer with GAS1 and PTEN inhibited cell invasion promoting cell death." (PMID 35280516, 2022). "Another study reported that loss of Hh ligand co-receptors, GAS1 and BOC, in mouse embryonic and pancreas cancer-associated fibroblasts (CAFs) led to partial suppression of pathway response to SHH and increased angiogenesis." (PMID 32108165, 2020). "We also included the down regulation or loss of function scenario of few proteins such as GAS1, SUFU, NUMB, SNO etc. in pancreatic cancer model." (PMID 23935937, 2013). "If stromal cells respond distinctly to SHH and IHH ligands, then IHH may play a more prominent role in angiogenesis in LAD than SHH due to the lower potency of IHH analogous to the diminished pathway response of Gas1−/−;Boc−/− fibroblasts in pancreatic cancer." (PMID 32108165, 2020). "In addition, Gas1 and Boc in conjunction with Cdon have recently been shown to modulate the levels of Hh-responsiveness in the pathogenesis of pancreatic cancer." (PMID 27811357, 2016). "Similarly, multiple HH co-receptors (Gas1, Boc, Cdon) regulate pancreatic tumor growth." (PMID 35867772, 2022). "GAS1 is a tumor suppressor involved in hedgehog signaling and RUNX3 is a transcription factor that is lost in pancreatic cancer and modulates metastatic potential." (PMID 27323855, 2016). "This included elements of the Hedgehog signaling pathway (SHH, GAS1), semaphorin signaling (SEMA3A, PLXNA1, PLXNB2, PLXND1, PLXNA2, FARP1, FARP2) and also axon guidance pathways (ROBO1, SLIT1, SLIT3 and SLITRK2), all notable for their involvement in pancreatic cancer progression and metastasis." (PMID 36429078, 2022).
colorectal cancer (8 papers, 2013 to 2024). A primary or metastatic malignant neoplasm that affects the colon or rectum. "A similar effect of Gas1 transfection was observed in the expression of Wars1, a gene whose low expression has been correlated with poor prognostic in colorectal cancer patients." (PMID 26161998, 2015). "Further studies showed that hsa-miR-33b-5p/GAS1 could affect the prognosis of patients with colorectal cancer, which may be beneficial to comprehend the molecular mechanisms of CRC liver metastasis and seek out new biomarkers for diagnosis and treatment." (PMID 33397428, 2021). "Also, the expression of GAS1 has been included in a test to discriminate between prostate cancer and benign tumors, its level being a prediction marker for metastasis or recurrence in stages II and III of colorectal cancer." (PMID 26161998, 2015).
melanoma (7 papers, 2009 to 2025). A malignant, usually aggressive tumor composed of atypical, neoplastic melanocytes. "The function of Growth arrest specific gene 1 (GAS1), a Hh ligand-binding factor, overlaps that of CDO and BOC and its downregulation is positively associated with cancer cells and melanoma metastasis, while its overexpression inhibits tumour growth." (PMID 23667323, 2013). "To address this, we screened protein expression of five melanoma metastasis suppressors (BRMS1, gelsolin, GAS1, NME1/NM23-H1, and KAI1) following KDELR3 knockdown." (PMID 31949145, 2020).
glioma (6 papers, 2015 to 2023). A benign or malignant brain and spinal cord tumor that arises from glial cells (astrocytes, oligodendrocytes, ependymal cells). "Each glioma patient was assigned a risk score according to the following formula: risk score = (0.2433)*RAB13 + (0.4201)*LYPLA1 + (0.0013)*GAS1 + (−0.0463)*VAMP2 + (0.5165)*CNIH4 + (0.3109)*PICK1 + (−0.0864)*RAB6B + (0.0978)*GOLT1." (PMID 37062068, 2023). "In this study, we have identified a novel mechanism involving Gas1 through which non-glioma associated microglia curb BTIC growth." (PMID 30327548, 2018). "Gas1 expression is linked to innate immune system components, microglia and macrophages, which are co-opted by gliomas." (PMID 30327548, 2018). "This supports the importance of Gas1 in inhibiting tumor progression and invites the potential of Gas1-modulating agents as anti-glioma treatments." (PMID 30327548, 2018). "Overall, our data suggest that non-tumor-suppressed innate immune cells can exert robust anti-tumor effects on BTICs by inducing Gas1, providing future impetus to search for innate immune cell stimulators that can be used therapeutically to combat gliomas." (PMID 30327548, 2018). "It would be of interest to determine whether Gas1 in BTICs is not induced by these glioma-associated microglia and such studies will be conducted in the future." (PMID 30327548, 2018). "As Gas1 affects growth suppression in several cancers, and since it has been shown that Gas1 induces cell cycle arrest and apoptosis in conventional glioma cell lines in vitro and in vivo, we tested the novel hypothesis that microglia elevate Gas1 expression in BTICs to reduce their growth." (PMID 30327548, 2018).
ovarian carcinoma (5 papers, 2018 to 2023). A malignant neoplasm originating from the surface ovarian epithelium. "For the obtained tissue samples from ovarian cancer and paracancer, qPCR showed that GAS1 was significantly highly expressed in the tumour samples, with significant differences in GAS1 transcript expression between the two groups." (PMID 37404304, 2023). "On this basis, we assessed the effect of GAS1 gene affecting the proliferation of ovarian cancer cell lines by colony assay." (PMID 37404304, 2023). "These datasets include acute lymphoblastic leukemial type L3 (ALL3), gastric 1 (Gas1), type 1 diabetes (T1D), myeloma (Mye), ovarian cancer (Ova), leukemia (Leuk), and mixed-lineage leukemial (MLL)." (PMID 36882446, 2023). "This firmly established the need for subsequent cellular experiments to clarify the specific effects of GAS1 on the regulation of invasion and metastasis in ovarian cancer cells." (PMID 37404304, 2023). "GAS1 was expressed at a very high level in glioblastoma compared to other cancer types and was only lower than GAS1 levels in ovarian cancers (OV) and sarcoma (SARC)." (PMID 30327548, 2018). "Particularly, siRNA-mediated knockdown of seven genes, CASC10, ATP11B, EMP1, GAS1, SLC6A15, GALNT13, and PDLIM3, significantly reduced cell proliferation of ovarian cancer cells." (PMID 35887085, 2022).
papillary thyroid carcinoma (4 papers, 2015 to 2019). "In addition, MIR34A can down-regulate GAS1 expression level and its overexpression could promote cancer cell proliferation, stimulate colony formation and suppress cell apoptosis in late-stage papillary thyroid cancer." (PMID 31126066, 2019).
gastric cancer (3 papers, 2016 to 2019). A primary or metastatic malignant neoplasm involving the stomach. "Based on a genomewide screen using a small interfering RNA library on gastric cancer cells, a report indicated that loss of function of the putative tumor suppressor gene GAS1 (growth arrest‐specific 1) was associated with a marked increase in epirubicin resistance." (PMID 30353671, 2018). "Subsequently, Gas1 was reported to be capable of inducing apoptosis in different cells, such as gliomas, gastric cancer, and even hippocampal neural cells." (PMID 27391369, 2016). "This point is supported by the previous clue regarding Gas1-induced cell apoptosis due to the Bax/Bcl-2 ratio and caspase-3 activation in gastric cancer." (PMID 27391369, 2016).
triple-negative breast carcinoma (3 papers, 2020 to 2024). An invasive breast carcinoma which is negative for expression of estrogen receptor (ER), progesterone receptor (PR), and human epidermal growth factor receptor 2 (HER2). "GAS1, which was associated with an increased risk of triple negative breast cancer (TNBC), is an essential co-receptor of hedgehog (Hh) signalling and specifically expressed at high levels in healthy fibroblasts." (PMID 38684708, 2024).
brain tumor (2 papers, 2018 to 2021). "Aberrant expression of GAS1 reduces tumorigenicity in human brain tumor-initiating cells, while downregulation of GAS1 expression is a potential biomarker of clear cell renal cell carcinoma." (PMID 33499877, 2021).
colon cancer (2 papers, 2013 to 2015). "We also considered the down regulation or loss of function of few tumor suppressor proteins such as GAS1, SUFU, NUMB, SNO etc., while simulating the colon cancer scenario, which in normal situation inhibited the GLI proteins." (PMID 23935937, 2013).
colorectal tumor (2 papers, 2021 to 2025). "In addition, in colorectal tumors, Bifidobacterium adolescentis activates the Wnt/β-catenin pathway and induce high expression of GAS1 in CD143+ CAFs; given the tumor-suppressive role of GAS1, this axis may provide novel therapeutic targets for probiotic-based modulation of the TME." (PMID 41516132, 2025).
Diabetes (2 papers, 2021 to 2022). "In addition, Gas1 deficiency in renal injury in the early stages of diabetes promotes the activation and proliferation of PECs, and they differentiate into podocytes." (PMID 34674704, 2021). "Diabetes favors a decrease in Gas1 expression and increased progenitor cell markers as well as WT1 in Bowman’s capsule cells." (PMID 34674704, 2021). "Hence, Gas1 might be a novel regulator of renal regeneration in diabetes." (PMID 34674704, 2021).
glioblastoma (2 papers, 2016 to 2018). The most malignant astrocytic tumor (WHO grade IV). "In concordance, glioblastoma patients with higher GAS1 expression are associated with significantly longer overall survival." (PMID 30327548, 2018). "Glioblastoma patients with high GAS1 expression were associated with significantly improved overall survival compared to those expressing low GAS1 (logrank P = 0.01)." (PMID 30327548, 2018). "We found that microglia increased the expression of Gas1 transcript and protein in glioblastoma patient-derived BTIC lines." (PMID 30327548, 2018). "Finally, we examined the expression of GAS1 in the four major glioblastoma subtypes (classical, mesenchymal, neural and proneural) in TCGA." (PMID 30327548, 2018). "To establish the validity of our findings in human glioblastoma samples, we examined GAS1 mRNA expression across 20 major cancer types in The Cancer Genome Atlas (TCGA), including glioblastoma (GBM)." (PMID 30327548, 2018).
hepatocellular carcinoma (2 papers, 2015 to 2023). A malignant tumor that arises from hepatocytes. "Most importantly, the present study shows that the antiproliferating effects of Gas1 on hepatoma cells can be extrapolated in vivo." (PMID 26161998, 2015). "Mice developing diethylnitrosamine-induced hepatocellular carcinoma were subjected to hydrodynamic gene delivery to overexpress Gas1 in liver." (PMID 26161998, 2015). "Given that Gas1 overexpression arrests cell proliferation at the G1/S interface in the Hepa 1–6 hepatoma cell line, we wondered whether Gas1 overexpression in liver could also affect proliferation of hepatoma cells in vivo." (PMID 26161998, 2015). "It has long been established that Gas1 overexpression arrests cell cycle before S phase in different cell lines, but its role in hepatoma cells remains unknown." (PMID 26161998, 2015).